SKP2 (S-phase kinase associated protein 2)
Diseases named in the same sentence as SKP2 in open-access papers (continued):
Sharing a sentence is not in itself a finding about the gene and the disease.
pituitary adenomas (1 paper, 2013). "The role of Skp2, which acts as an an oncogene through targeting p27kip1 for degradation, has been observed in a wide variety of tumors, including some pituitary adenomas." (PMID 23667519, 2013). "We show that the carotenoids act on ACTH-secreting pituitary adenoma cells by regulating the phosphorylation of connexin 43, and the content of Skp2 and p27Kip1." (PMID 23667519, 2013). "Lycopene and beta-carotene are able to produce these effects by a mechanism that probably involves the regulation of connexin 43, Skp2 and p27kip1 expression, suggesting that these compounds might correspond to novel pharmacological approaches for the treatment of pituitary adenomas." (PMID 23667519, 2013).
premature ovarian failure (1 paper, 2021). "Furthermore, SKP2 is pivotal for the maintenance of fertility, and defects in SKP2 may underlie the pathogenesis of abnormal gamete production and premature ovarian failure during the reproductive life of women." (PMID 34116705, 2021).
pterygium (1 paper, 2011). A wedge-shaped fibrovascular lesion arising from the bulbar conjunctiva and extending to the cornea. "In the present study, we investigated if small interfering RNA (siRNA)-mediated gene silencing of S phase-kinase-interacting protein 2 (Skp2) can be employed to inhibit protein 27 kinase inhibition protein 1 (p27kip1) down-regulation in pterygium fibroblast cells (PFC) in vitro and in vivo." (PMID 21270971, 2011). "In view of the growing interest in Skp2 and p27kip1 as a target for drug development in inhibition of hPFC proliferation after surgery, it is our hope that the data presented here will help to promote going efforts to decrease the recurrence of pterygium after surgery." (PMID 21270971, 2011).
respiratory infections (1 paper, 2025). "Further studies on respiratory infections caused by MERS-CoV showed that the virus induces AKT1 activation through phosphorylation, which in turn activates S-phase kinase-associated protein 2 (SKP2)." (PMID 40136667, 2025).
rhabdomyosarcoma (1 paper, 2023). A rare aggressive malignant mesenchymal neoplasm arising from skeletal muscle. "Here the authors show that SKP2 is epigenetically regulated by the muscle lineage transcription factor MYOD, supports tumorigenesis in the Fusion Negative (FN) subtype of rhabdomyosarcoma (RMS) and impairs differentiation promoting degradation of p57Kip2." (PMID 38102140, 2023).
serous ovarian tumor (1 paper, 2014). "In addition, immunohistochemical staining for cyclin E, SKP2 and stathmin was performed on a total of 80 paraffin-embedded serous ovarian tumor tissue samples." (PMID 25106448, 2014).
Sertoli Cell-Only Syndrome (1 paper, 2006). A type of male infertility in which no germ cells are visible in any of the biopsied SEMINIFEROUS TUBULES (type I) or in which germ cells are present in a minority of tubules (type II). "We now show that disruption of Skp2 in mice results in a marked impairment in the fertility of males, with the phenotypes resembling Sertoli cell-only syndrome in men." (PMID 16759351, 2006). "The marked depletion of spermatogenic cells apparent in adult Skp2-/- males is reminiscent of that in infertile men with Sertoli cell-only syndrome." (PMID 16759351, 2006).
silicosis (1 paper, 2021). Silicosis is a respiratory disease caused by breathing in (inhaling) silica dust. "RT‐qPCR analysis revealed a significantly increased E2F1 expression pattern in silicosis, which was highly positively correlated with the expression pattern of SKP2." (PMID 34428336, 2021). "Immunohistochemical staining suggested that the SKP2‐positive cells were significantly increased in the alveolar tissues of mice with early silicosis compared to the normal alveolar tissues." (PMID 34428336, 2021). "To further verify whether SKP2 was elevated in early silicosis, we analysed the SKP2 mRNA levels in the afore‐mentioned tissues by RT‐qPCR and confirmed the presence of a significantly increased SKP2 expression pattern in the alveolar tissues of early silicosis." (PMID 34428336, 2021). "Decreased Beclin1 and increased SKP2 and E2F1 were identified in mice with silicosis." (PMID 34428336, 2021). "Moreover, the mice with silicosis following treatment of miR‐205‐5p agomir showed upregulated expression patterns of Col1a1, Col3a1 and LC3, while this upregulation was annulled by Lenti‐E2F1, Lenti‐SKP2 or siBeclin1." (PMID 34428336, 2021).
skin cancer (1 paper, 2024). "Furthermore, our data on the treatment with Bortezomib (BTZ), a proteasome inhibitor, show a decrease in MTH1 levels in A431 and A388 skin cancer cell lines, correlating with the downregulation of Skp2." (PMID 38724504, 2024).
testicular germ cell tumor (1 paper, 2023). A germ cell tumor arising from the testis. "As a result, the positive relevance of immune neoantigen count with SKP2 expression was detected in SARC, TGCT (testicular germ cell tumors), and LUAD (p < 0.05)." (PMID 37308972, 2023).
type 2 diabetic (1 paper, 2018). "Urinary miR-378i levels were elevated in both db/db mice and type 2 diabetic patients, whereas decreased Skp2 levels were shown in proximal tubule of db/db mice and human DN." (PMID 30469549, 2018). "Transcriptome analysis of PTECs from a type 2 diabetic patient and a normal individual using next generation sequencing (NGS) and systematic bioinformatics analyses indicated that miR-378i and its downstream target S-phase kinase protein 2 (Skp2) contribute to HG-induced senescence in PTECs." (PMID 30469549, 2018).
urothelial carcinoma (1 paper, 2021). A malignant neoplasm derived from the transitional epithelium of the urinary tract (urinary bladder, ureter, urethra, or renal pelvis). "It has been shown that the increased SKP2 mRNA levels contributed to the progression and predicted poor prognosis in human urothelial carcinoma." (PMID 33478005, 2021).
uterine cancer (1 paper, 2021). Primary or metastatic malignant neoplasm involving the uterine corpus and/or the cervix. "SKP2 mutations occur most frequently in bladder, colorectal, skin and uterine cancers and result in key amino acid substitutions, including L105F (uterine) and S135C (bladder), that are located within the F-box motif, which is critical for interactions between SKP2 and the SCF complex." (PMID 35008511, 2021). "Unlike SKP2, there are “deleterious” and “possibly/probably damaging” substitutions in all 10 cancer types assessed, with the highest incidences occurring in breast, head and neck and uterine cancers." (PMID 35008511, 2021).
cancer (344 papers, 2005 to 2026). A tumor composed of atypical neoplastic, often pleomorphic cells that invade other tissues. "SKP2 overexpression induces hyperplasia, mPIN and low-grade carcinoma associated with increased SKP2 expression and cell proliferation and decreased expression of p27Kip1." (PMID 41542047, 2026). "F-Box and WD repeat domain containing 2 (FBXW2) is an E3 ligase that inhibits cancer migration, invasion, and metastasis by promoting the degradation of oncogenic proteins, such as S-phase kinase associated protein 2 (SKP2) and β-catenin." (PMID 40299435, 2025). "SKP2 is frequently upregulated in various types of cancers and is associated with cancer progression and metastasis." (PMID 40806307, 2025). "Previous studies have reported that the loss of Skp2 was sufficient to prevent tumorigenesis in Rb1-deficient mice, supporting a dependent role for SKP2 in Rb1-inactivated cancers." (PMID 38355807, 2024). "In several types of human cancer, high levels of Skp2 expression are linked to poor prognosis and unfavorable therapy outcomes." (PMID 38341584, 2024). "Skp2, an oncoprotein and ubiquitin ligase, has been implicated in carcinogenesis and linked to poor prognosis in various human cancers, including oral squamous cell carcinoma." (PMID 38724504, 2024). "Dysregulation of Skp2 and its interaction with epigenetic processes are associated with various diseases, including cancer." (PMID 38559562, 2024). "Loss of RB1 protein function, commonly observed through RB1 mutations in aggressive cancers, leads to dysregulation of SKP2 activity, resulting in decreased levels of p27 and compromised cell cycle control." (PMID 38672640, 2024). "It’s worth noting that overexpression of Skp2 is required for the survival of aggressive cancer cells harboring multiple mutations of tumor suppressor genes." (PMID 38561375, 2024). "Consistently, SKP2 targeting causes cell cycle arrest of cancer cells and halts tumorigenesis in vivo." (PMID 38102140, 2023). "Based on 19,515 samples from multiple sources, for the first time, this study provided an overview of gene S-phase kinase associated protein 2 (SKP2) in pan-cancer." (PMID 37308972, 2023). "Based on 19,515 samples from several sources, for the first time in an overview of pan-cancer, this study disclosed the overexpression of SKP2 and its risk factor for the prognosis of patients in multiple neoplasms." (PMID 37308972, 2023). "SKP2 is overexpressed in various human cancers and is associated with poorer survival and poor therapeutic outcome, suggesting a role for SKP2 in tumorigenesis." (PMID 37512088, 2023). "Over-expressed SKP2 represented a risk factor for the prognosis of most cancer patients (hazard ratio > 1, p < 0.05)." (PMID 37308972, 2023). "Increased SKP2 levels are associated with the development and progression of various human cancers, including PCa." (PMID 37491794, 2023). "Overexpression of Skp2 has been observed in various human cancers associated with reduced survival and is considered to have oncogenic activity." (PMID 38203554, 2023). "Skp2 was reported to be overexpressed in various aggressive cancers both at mRNA level and protein level since its discovery, and the protein level of Skp2 was reported to associate with the prognosis in various cancer patients." (PMID 37089937, 2023). "SKP2 overexpression has been associated with poor patient survival and drug resistance in a variety of human cancers and its reported oncogenic properties appear to be linked mainly to reduced p27 levels allowing increased tumor cell proliferation." (PMID 35673965, 2022). "SKP2 not only functions as an oncoprotein, but has also been identified in cancer-associated drug resistance." (PMID 35741710, 2022).
cancer (continued). "Our findings suggest that the relative expression levels of SKP2 and/or p27 can be linked to a therapeutic vulnerability and be exploited to stratify cancer patients considered for treatment with CHK1i." (PMID 35673965, 2022). "Owing to its vital role in cell-cycle regulation, SKP2 plays a critical role in human cancers, where its overexpression is associated with poor survival and adverse therapeutic outcomes." (PMID 36326820, 2022). "It was reported that aberrant Skp2 expression and dysregulation of its activity were closely associated with various human cancers." (PMID 35685435, 2022). "SKP2 is overexpressed in a variety of human cancers and associated with poor prognosis by enhancing tumor progression." (PMID 35831273, 2022). "S-phase kinase-associated protein 2 (SKP2) is overexpressed in a variety of human cancers and is associated with poor prognosis by enhancing tumor progression." (PMID 35831273, 2022). "SKP2 is an oncogene and is overexpressed in a variety of cancers, and associated with multiple tumor progressions and poor prognosis." (PMID 36293387, 2022). "Another group of proteins related to the malignancy of cancer is the S-phase kinase-associated protein 2 (SKP2) that belongs to the protein complex of Skp, Cullin, and F-box (SCF complex)." (PMID 34571823, 2021). "Skp2 not only functions as a pro-survival gene in tumor progress, but also is involved in cancer-associated drug resistance." (PMID 34068643, 2021). "In agreement with this, SKP2 scored as a SL partner for RB1-deficient cells in both cancer cell line analysis and human cancer patients." (PMID 33591981, 2021). "An overexpression of S-phase kinase-associated protein 2 (SKP2) is frequently observed in human cancer progression and metastasis, and evidence suggests that SKP2 plays a proto-oncogenic role both in vitro and in vivo." (PMID 34414959, 2021). "Several types of mutation and amplification of SKP2 have been detected in various types of cancer, including cervical, endometrial, adrenocortical, ovarian, breast, and non-small-cell lung cancer." (PMID 32429232, 2020). "Similar to the SE‐associated genes, this coregulated gene group includes a known FP‐RMS disease‐promoting gene, SKP2, and 13 additional genes implicated in cancer promotion (based on a survey of published literature), but not previously studied in RMS." (PMID 32697014, 2020). "Some studies showed that Skp2 deficiency impairs Akt activation, glucose transporter 1 expression, and glucose uptake and glycolysis, suppressing cancer progression in various tumor models." (PMID 32796841, 2020). "Upregulation of Skp2 has been observed in many cancers, and high expression of Skp2 is often associated with poor prognosis." (PMID 33234069, 2020). "This guaianolide inhibits the in vitro ubiquitination of p27Kip1 by SCFSkp2—the ubiquitin ligase (SCF) complex with S-phase kinase-associated protein 2- stabilizes p27Kip1 levels in HeLa cells and inhibits the growth of human and mouse cancer cells." (PMID 33371413, 2020). "The E3 ligase TRAF6-, TRAF4-, and Skp2-mediated K63-linked ubiquitination of AKT is required for AKT activation in human cancer cells." (PMID 32357935, 2020). "Statins were also found to act as S-phase kinase-associated protein 2 (SKP2) inhibitors in several cancer cells, which resulted in p27 protein accumulation by preventing proteasomal degradation." (PMID 32731382, 2020).
cancer (continued). "As a transcription factor, FOXM1 has many target genes including KIF20A, CENPF, CCNB1, MYC, NIMA-related kinase 2, MMP2, MMP9, and S-phase kinase-associated protein 2 that are implicated in cancer initiation, progression, or drug resistance." (PMID 31072351, 2019). "High expression of Skp2 in tumors, accompanied by p27Kip1 downregulation, has been correlated with poor prognosis in cancer patients; Skp2 has also been implicated as a prognostic marker in many types of cancer, including prostate cancer." (PMID 30952903, 2019). "As well as targeting Rb-defective TNBC, the potential for using SKP2 inhibition in other cancer histologies associated with Rb defects is considerable." (PMID 29915391, 2018). "Altered expression and mutations in several F-box proteins, including SKP2, are hallmarks of several cancers." (PMID 29594129, 2018). "Overexpression of Skp2 is well known for its strong association with aggressive tumour behaviour and poor clinical outcome in a variety of cancers, including HCC21." (PMID 29396392, 2018). "Skp2 overexpression has been shown to be predictive of cancer progression and associated with a poor prognosis." (PMID 30250282, 2018). "Up to this point, it is interesting to note that in both cell lines, MP-HX downregulated all six top-ranked genes (PLK1, MCM2, MCM3, MCM7, MCM10 and SKP2) that were proposed to be cancer-associated (Wu, Zhu & Zhang, 2012)." (PMID 30042885, 2018). "As an oncoprotein, S-phase kinase associated protein 2 (Skp2) has also been reported activated in many types of cancers, included approximately 50% patients with GC." (PMID 28446188, 2017). "High expression of SKP2 has been implicated in human cancer development and progression including HNSCC and has become a promising therapeutic target." (PMID 28030848, 2017). "Many of the recent studies have reported the essential role that SKP2 play in the degradation of p27Kip1 in association with various cancers." (PMID 26956626, 2016). "Studies showed that Skp2 deficiency impairs Akt activation, glucose transporter 1 expression, and glucose uptake and glycolysis, and suppresses cancer progression in various tumor models." (PMID 26799418, 2016). "Overexpression of Skp2 has been identified and is associated with poor prognosis in various types of human cancers." (PMID 26046466, 2015). "S-phase kinase associated protein 2 (Skp2) is overexpressed in several human cancers and associates with poor prognosis." (PMID 25015320, 2014). "In many cancers, the increased expression of Skp2 is usually associated with the reduced expression of p27." (PMID 23437233, 2013). "The present results suggest that wogonin has multiple anti-cancer effects associated with degradation of c-Myc, SKP2, HDAC1 and HDAC2." (PMID 24265759, 2013). "Substantial evidence supports the oncogenic role of the E3 ubiquitin ligase S-phase kinase-associated protein 2 (Skp2) in many types of cancers through its ability to target a broad range of signaling effectors for ubiquitination." (PMID 23071779, 2012). "The Skp2 (S-phase kinase associated protein 2) oncoprotein is often highly expressed in various types of human cancers." (PMID 23230084, 2012). "Recent studies reveal that the overexpression of Skp2 is associated with the progression of a variety of human cancers." (PMID 22533738, 2012). "Increased levels of Skp2 are observed in various types of cancer and associated with poor prognosis." (PMID 23300741, 2012). "In the present study, we initially showed that high expression of Skp2 in tumor cell nuclei was associated with advanced local invasion of primary carcinoma." (PMID 22533738, 2012).